TTTY17A (testis expressed transcript, Y-linked 17A)
Synonyms: NCRNA00140; TTTY17
Gene: Long non-coding RNA gene on chromosome Y (22,851,584 to 22,852,715, forward strand). Ensembl gene ENSG00000228240.
Homologues: Paralogues in human: TTTY17B (100% identical).